CCNF (cyclin F)
Diseases named in the same sentence as CCNF in open-access papers (continued):
Sharing a sentence is not in itself a finding about the gene and the disease.
cancer (continued). "In this context, it is essential that overexpression of CCNF is positively correlated with proliferation-promoting genes, suggesting that it contributes to cancer progression and therefore poor patient prognosis by promoting excessive cell proliferation." (PMID 38654021, 2024). "The differences in CCNF expression between cancer tissues and normal tissues and between cancer tissues and paracancerous tissues for 33 kinds of cancer were analyzed by Xiantao Academy." (PMID 37168372, 2023). "The R language was used to analyse the correlation of the CCNF gene and immune checkpoint gene across cancers." (PMID 37168372, 2023). "In our study, CCNF was generally highly expressed in 33 cancer types, and the results were cross-validated with the TIMER 2.0, GEPIA2 and Xiantao Academic online databases." (PMID 37168372, 2023). "The co-expression analysis revealed that, in most cancers, CCNF expression positively correlated with genes related to chemokines, immune activation, chemokine receptors, major histocompatibility complex (MHC), and immunosuppression." (PMID 37670965, 2023). "To explore the biological significance of CCNF expression in pan-cancer, we retrieved 100 genes with similarity to CCNF from the GEPIA2 database." (PMID 37670965, 2023). "The results showed that CCNF activated 69% of the cell cycle and 25% of apoptosis in cancer, while inhibiting 18% of the Ras/MAPK and Hormone ER pathways in cancer." (PMID 37670965, 2023). "At present, there are only a few single-cancer analyses on the correlation between CCNF and cancer features using the TCGA database." (PMID 37168372, 2023). "In this study, we investigated the potential role and mechanism of CCNF in pan-cancer using using an advanced pan-cancer analysis system." (PMID 37670965, 2023). "In conclusion, our study provides further evidence supporting the oncogenic role of elevated CCNF expression in cancer and emphasizes its potential as a promising target for tumor therapy." (PMID 37670965, 2023). "MethSurv was used to analyze the effects of the methylation levels of CCNF on patient survival/prognosis across cancers." (PMID 37168372, 2023). "The R language was used to analyze the expression of CCNF and the immune score and matrix score across cancers." (PMID 37168372, 2023). "The correlation between the mRNA expression of CCNF and the clinicopathological stages of 27 cancer types was analyzed by GSCA." (PMID 37168372, 2023). "The differences in CCNF expression between cancer tissues and normal tissues for 33 kinds of cancer were analyzed by GEPIA2." (PMID 37168372, 2023). "Nonetheless, our study lays a significant groundwork for comprehending the role of CCNF in cancer and provides valuable insights for the future development of precise targeted therapies and immunotherapy." (PMID 37670965, 2023). "We conducted further exploration of the genetic alterations of CCNF in pan-cancer utilizing the cBioPortal database." (PMID 37670965, 2023). "The expression of DNA methylation-regulated genes is closely associated with cancer, and we calculated the promoter methylation levels of CCNF in pan-cancer using the UALCAN database." (PMID 37670965, 2023). "CCNF, as a key component of the ubiquitin proteasome, may maintain genome integrity by mediating the degradation of intracellular proteins, while overexpression of CCNF causes dysregulation of DNA replication, repair and cell cycle checkpoints, thereby inducing the progression of cancer cells." (PMID 37168372, 2023). "The UALCAN database was applied to compare the expression of CCNF in different sex and race subgroups with in the same cancer cohort." (PMID 37168372, 2023). "For the first time, we analyzed the differential expression of CCNF across cancers and its correlation with clinical prognosis." (PMID 37168372, 2023). "Our findings shed light on the potential of CCNF as a promising avenue for novel cancer treatment and prevention strategies." (PMID 37670965, 2023).
cancer (continued). "Given the recurrent activation of the PI3K-AKT pathway in many cancers, it will be interesting in the future to determine if cyclin F phosphorylation promotes p130 degradation." (PMID 34851822, 2021). "Analysis of the Cancer Dependency Map reveals that CCNF is highly correlated with the CDK-RB network." (PMID 34851822, 2021). "The profile of expression of UBA1, UBE2C, UBE2T, UBE2O, and CCNF in BRCA seemed to support their involvement in cancer initiation and progression." (PMID 34201347, 2021). "As such, we conducted in vitro experiments to confirm the role of CCNF in the proliferation of LUSC cells, which was following a previous study on the role of CCNF in cancers and the CCNF expression in LUSC in TCGA." (PMID 34112238, 2021). "Altogether, we propose a signature network of E3 ligases that collaboratively modulates CCNF anti-cancer activity." (PMID 34201347, 2021). "Likewise, blocking p130 degradation could phenocopy CDK4/6 inactivation and could potentially be therapeutically advantageous, and would be consistent with our analysis showing that loss-of-function in cyclin D, CDK4, and cyclin F are highly correlated across nearly 800 cancer cell lines." (PMID 34851822, 2021). "In this study, we retrospectively profiled the transcriptome of BRCA tissues and found a notable upregulation of four SCFF-box E3 ligases (FBXL8, FBXO43, FBXO15, and CCNF) in the carcinoma tissues." (PMID 34201347, 2021). "We believe that these contacts between Psd1 and cyclin F can disturb the interaction of cyclin F with their endogenous substrates, some of which are related to cancer diseases." (PMID 32290394, 2020). "In the future, it would be crucial to establish cancer models that mimic cyclin F amplification both in vivo and in vitro." (PMID 31424118, 2019). "These cellular regulatory functions mediated by cyclin F have enabled researchers to consider cyclin F as a potential molecular target in cancer therapeutics." (PMID 28184007, 2017). "Increasing evidence also suggests the involvement of cyclin F/CCNF in cancer." (PMID 38654021, 2024). "Regarding patient 3, the WES did not detect any reported known cancer-driver mutations, so we analyzed the ctDNA levels of two somatic mutations in the CCNF and CEP135 genes, and custom-designed probes were used." (PMID 39596073, 2024). "Mechanistically, our bioinformatics analyses suggest that CCNF may act as an oncogene in ccRCC via promoting cancer cell proliferation and affecting the tumor immune microenvironment." (PMID 38654021, 2024). "Furthermore, data from the CTD database revealed chemicals affecting CCNF methylation, including Aflatoxin B1, aflatoxin B2, benzo(e)pyrene, Methapyrilene, and Valproic Acid, which increased the methylation level of CCNF in cancer." (PMID 37670965, 2023). "However, the exploration of CCNF's role has been confined to a limited number of tumor types, and its potential as an immunotherapeutic target in pan-cancer settings has yet to be investigated." (PMID 37670965, 2023). "Although the pancancer expression of CCNF and its effect on clinical prognosis have not been reported, existing studies suggest that there may be a close relationship between CCNF and the occurrence and development of cancer." (PMID 37168372, 2023). "Overexpression of CCNF reduces immune and stromal cell infiltration in many cancers." (PMID 37168372, 2023).
cancer (continued). "It is important to note that the up- or down-regulation of these signaling pathways by CCNF may exhibit variation across different cancer types, warranting further exploration into the specific mechanisms underlying their regulation of cancer." (PMID 37670965, 2023). "Effects of sex and race differences on CCNF expression in the same cancer type." (PMID 37168372, 2023). "Furthermore, by assessing the expression of CCNF in normal and cancer cell lines from the BioGPS database, we observed that the overall expression level of CCNF was generally higher in cancer cell lines compared to normal cell lines." (PMID 37670965, 2023). "The results of this study could provide helpful information for further exploring the complex relationship between CCNF and multiple cancer types." (PMID 37168372, 2023). "In addition, the expression level of CCNF protein in cancer tissues and normal tissues for multiple cancer types was compared analysis of immunohistochemical staining data in the HPA database." (PMID 37168372, 2023). "Additionally, we investigated the interrelation between CCNF expression, DNA methylation profiles, and immune infiltration levels in 33 different cancer types." (PMID 37670965, 2023). "Finally, RT-qpcr and WB assays were employed to assess CCNF expression in established cancer cell lines." (PMID 37670965, 2023). "And among them, the expression of CCNF was significantly increased in paired samples of 13 cancers." (PMID 37670965, 2023). "While initial evidence suggests a tumor-suppressor function for cyclin F, emerging reports indicate that it may also have a context-dependent oncogenic function in certain cancers." (PMID 36342772, 2022). "In support of our findings, future studies would be warranted to explore whether CCNF is commonly downregulated by ubiquitination in other cancers." (PMID 34201347, 2021). "However, the overexpression of CCNF inhibited cancer cell progression, indicating its anti-tumorigenic role." (PMID 34201347, 2021). "Thus, CCNF-triggered RRM2 reduction (in the CCNF-RRM2 axis) likely unleashes anti-cancer mechanisms against BRCA." (PMID 34201347, 2021). "The overexpression of CCNF inhibited cancer cell progression, indicating its anti-tumorigenic role." (PMID 34201347, 2021). "Thus, we propose that CCNF plays a cancer suppressor role, but its protein level is downmodulated in the disease, probably via FBXL8/FZR1-mediated degradation." (PMID 34201347, 2021). "These complex regulation mechanisms mediated by cyclin F could be significant to the cancer field, since aberrant expression of RRM2 has been found in multiple types of cancers and failure to maintain the balance of dNTP can cause genome instability." (PMID 31475738, 2019). "Therefore, CCNF is often correlated with a poor prognosis in cancer patients." (PMID 37168372, 2023). "Additionally, CCNF expression influenced genetic alterations in pan-cancer." (PMID 37670965, 2023). "In our study, the expression level of CCNF in Caucasians with BLCA and THYM cancer was significantly lower than that in African Americans but significantly higher than that in Asians." (PMID 37168372, 2023). "The correlation of CCNF expression with OS and RFS for 21 cancer types was evaluated by Kaplan-Meier Plotter." (PMID 37168372, 2023). "The correlation between CCNF expression and TMB and MSI in 33 cancer types was analyzed with R based on the UCSC Xena database." (PMID 37168372, 2023). "Cyclins and cyclin-dependent kinases (CDKs) are major effectors of the cell cycle with key role in cancer where our data shows downregulation of key cell-cycle proteins such as cyclin D1 and Geminin and mRNA levels of CCNE1, CCNF, CDK1, CDK2 and CDK5." (PMID 35902556, 2022).
cancer (continued). "To comprehensively understand these four lncRNAs (LINC01224, CASC9, LINC00346, and TRPM2-AS) and seven target mRNAs (CCNF, PKMYT1, GCH1, TK1, PSAT1, ADAM33, and DDX11), we performed genome instability, immune, cancer stemness, and drug sensitivity analysis." (PMID 34368141, 2021). "Among all cyclin genes analyzed, CCNA2, CCNE2, CCNB2, CCNB1, CCNF, and CCNE1 were most elevated in the included cancers." (PMID 33996604, 2021). "Analysis of the CTRP (Cancer Therapeutics Response Portal) and GDSC (Genomics of Drug Sensitivity in Cancer) databases revealed that the sensitivity to multiple antitumor drugs increased when CCNF was highly expressed." (PMID 39895786, 2025). "RT-qpcr and WB assays further confirmed that CCNF expression was higher in human cancer cell lines than in normal cell lines." (PMID 37670965, 2023). "PPI interaction network analysis showed that the CCNF gene, CDK1 gene and CDC6 gene are closely related, indicating that these genes, as key regulators of the G2/M or G1/S checkpoint of the cell cycle, promote the occurrence and progression of many cancers." (PMID 37168372, 2023). "The expression of CCNF in ACC, KICH, KIRC and KIRP was the highest in clinical stage IV tumors, which may contribute to a poor prognosis and cancer progression." (PMID 37168372, 2023). "CCNF is overexpressed across cancers and is an adverse prognostic factor in terms of OS and RFS in many cancers; this phenomenon may be related to hypomethylation of the CCNF gene, which could lead to cancer progression and worsen prognosis." (PMID 37168372, 2023). "In addition, CCNF overexpression also reduced the infiltration of immune cells and stromal cells in GBM, LGG, LUAD and UCEC cancers, thereby promoting the growth of tumor tissues." (PMID 37168372, 2023). "The results demonstrated that CCNF expression exhibited negative correlations with immune cells in most tumors, while also showing significant positive correlations in certain cancers." (PMID 37670965, 2023). "The expression level of CCNF in male patients with HNSC (P=0.0010) and LUAD (P=0.0329) was significantly higher than that in female patients, but CCNF expression in male patients with KIRP (P=0.0161) and SARC (P=0.0064) was significantly lower than that in female patients with these cancers." (PMID 37168372, 2023). "In addition, chemicals impacting CCNF methylation were obtained through the CTD database, and these findings may be helpful for methylation therapy in cancer." (PMID 37670965, 2023). "Nonetheless, a comprehensive exploration of CCNF's involvement in pan-cancer remains lacking." (PMID 37670965, 2023). "However, CCNF-associated mechanisms are not fully clarified in BRCA, although its binding partner RRM2 (an oncogenic factor) was found to be overexpressed in numerous cancers, including BRCA." (PMID 34201347, 2021). "The immunohistochemical staining results from HPA database indicated significantly higher positivity for AURKA, CCNB1, CCNF, and EXO1(Not found in HPA database) in cancer tissues than in adjacent normal tissues." (PMID 31087508, 2019).
tumor (25 papers, 2012 to 2025). "CCNF expression was also correlated with immune cell infiltration and caused poor outcomes depending on the abundance of tumor-infiltrating immune cells in ccRCC." (PMID 38654021, 2024). "In this study, we investigated the differential expression of CCNF across various tumor stages to assess its potential as a diagnostic marker." (PMID 37670965, 2023). "These analyses focused on exploring CCNF expression, prognosis, gene mutations, immune cell infiltration, DNA methylation levels, and targeted chemical drugs across different tumor types." (PMID 37670965, 2023). "CCNF encodes a component of the SCFCyclin F E3 ubiquitin ligase with various roles in the cell cycle and was proposed to function as a tumor suppressor." (PMID 37639469, 2023). "Our findings revealed significant associations between CCNF expression and infiltration levels of multiple tumor immune cells, particularly Th2 cells, CAFs, Tfh cells, and MDSCs across various tumor types." (PMID 37670965, 2023). "Additionally, we examined the association between CCNF expression and tumor prognosis using Cox regression and Kaplan-Meier survival analysis." (PMID 37670965, 2023). "Moreover, there was a trend toward the association of CCNF status with tumor grade (p = 0.107)." (PMID 38654021, 2024). "High expression of cyclin F/CCNF is an unfavorable prognostic factor that correlates with aggressive tumor phenotype and poor patient survival." (PMID 38654021, 2024). "The relationship between immune cell infiltration level and CCNF expression in ccRCC was investigated using the Tumor Immune Estimation Resource 2.0 (TIMER2) and Gene Expression Profiling Interactive Analysis 2 (GEPIA2)." (PMID 38654021, 2024). "Using tumor biopsy-derived tumor DNA as a positive control in dPCR, we observed mutation prevalence rates of 33% for the CEP135 gene and 34% for the CCNF gene." (PMID 39596073, 2024). "In the tumor tissues of both cohorts, cyclin F staining was predominantly cytoplasmic, with mixed membranous-cytoplasmic staining or solely membranous staining observed in the same cases." (PMID 38654021, 2024). "Statistical analysis showed a significant increase of cyclin F expression in ccRCC compared to tumor-adjacent normal tissue or normal renal tissue." (PMID 38654021, 2024). "Another aspect of this study was to estimate the relevance between the CCNF and tumor immune infiltration in TCGA-KIRC." (PMID 38654021, 2024). "In the TMA_1 cohort, ccRCCs with increasing tumor grade more frequently had cyclin F-high than cyclin F-low expression (p = 0.018)." (PMID 38654021, 2024). "Here, by integrating analyses through IHC, RNA-seq, and gene chip microarray data, we reproducibly found the remarkable differences in CCNF protein and gene expression levels between tumor and control tissues." (PMID 38654021, 2024). "To comprehend the role of CCNF in the tumor microenvironment, we investigated its correlation with tumor-infiltrating immune cells." (PMID 37670965, 2023). "The correlation between CCNF expression and tumor immune cell infiltration was evaluated using the TIMER2 database." (PMID 37670965, 2023). "CCNF holds promise as an invaluable early detection indicator and tumor biomarker, offering potential targets for tumor treatment and prevention." (PMID 37670965, 2023). "Tumor tissues with high expression of CCNF showed high immune infiltration, and the expression of CCNF was partially positively correlated with tumor-infiltrating CD4+ T cells, CD8+ T cells, B cells, macrophages, neutrophils, and dendritic cells." (PMID 34397798, 2021). "The methylation of the CCNF gene in adjacent normal tissues was higher than that in tumor tissues (P = .014), and the methylation of CCNF was negatively correlated with the expression of CCNF." (PMID 34397798, 2021).